LEP (leptin)
Diseases named in the same sentence as LEP in open-access papers (continued):
Sharing a sentence is not in itself a finding about the gene and the disease.
metabolic syndrome (continued). "Furthermore, and as already mentioned, atherogenic dyslipidemia is a component of metabolic syndrome, the occurrence of which is associated with high leptin levels." (PMID 36289903, 2022). "Our results were in agreement with previously published reports which demonstrated that telmisartan could ameliorate metabolic syndrome associated nephropathy by reducing leptin release from the perirenal adipose tissue." (PMID 33761942, 2021). "Metabolic syndrome, with dyslipidemia as one of its components, may increase the risk of breast cancer by increasing leptin and decreasing adiponectin levels in blood, as depicted by authors from the USA." (PMID 34022902, 2021). "Furthermore, metabolic changes were observed in one severely obese subject with the LEP wt/- variant p.H118L, who showed hypertension, metabolic syndrome, and hepatic steatosis." (PMID 34448070, 2021). "Our findings suggest ANGPTL8, particularly interacting with leptin, might have a protective role in cardiac remodeling among youths with risk for metabolic syndrome." (PMID 35145478, 2021). "Moreover, previous studies have demonstrated that dopamine agonist treatment can reduce hypothalamic NPY levels in the ob/ob leptin-deficient genetic model of metabolic syndrome." (PMID 34200262, 2021). "Normal growth could be explained by hyperinsulinemia and elevated leptin levels, which might be caused by dyslipidemia." (PMID 33327247, 2020). "The higher leptin level increased the risk of metabolic syndrome in Taiwanese individuals." (PMID 31914480, 2020). "Leptin can improve dyslipidemia in insulin-deficient rodents." (PMID 33071988, 2020). "Furthermore, leptin is an established regulator of body weight, and leptin/adiponectin dysregulation has been associated with cardiovascular disease, metabolic syndrome, and nonalcoholic fatty liver disease (DiNicolantonio, Lucan, & O'Keefe, 2016)." (PMID 31625260, 2020). "Thus, reduced PPARγ activity in APL cells decreased leptin but increased resistin expression, causing lipid metabolism disorder in hepatocytes and subsequent dyslipidemia in mice." (PMID 32929351, 2020). "Thirdly, whereas both leptin and adiponectin are related to dyslipidemia, the Trp64Arg variant may indirectly affect lipids levels through the mediation of adipokines." (PMID 32430022, 2020). "The adiponectin/leptin ratio was reported to be associated with insulin sensitivity, and our study in agreement with previous document demonstrated that this ratio contributed to the metabolic syndrome." (PMID 31341853, 2019). "Moreover, the circulating miRNA profiles were associated with the plasma leptin level in metabolic syndrome, and miRNAs were found to be involved in hypothalamic leptin sensitivity." (PMID 31408957, 2019). "First, it is evident that the aberrant adipokine production not only renders the susceptibility to metabolic syndromes in genetically deficient rodent models of various adipokines but also the vulnerability to neurodegeneration, especially in models of impaired leptin-signaling." (PMID 31718027, 2019). "Dopaminergic agonists such as bromocriptine suppress insulin and leptin release by reducing peak amplitude of their rhythmic release, and have been associated with improved metabolic function in obese subjects with metabolic syndrome, and subjects suffering from T2D." (PMID 30364286, 2018). "Furthermore, it has been also reported that the concentration of leptin in relation to adipose mass in humans, decreases as factors associated with metabolic syndrome worsen, especially in hypertriglyceridaemia." (PMID 28265495, 2017). "Interestingly, TA patients have a greater prevalence of metabolic syndrome and higher levels of leptin and resistin, associated with upregulated inflammatory markers such as pentraxins-3, compared to age-matched controls." (PMID 29234289, 2017).
metabolic syndrome (continued). "After adjustment for age and sex, the LAR was also found to be significantly associated with metabolic syndrome (OR = 1.573, p value =0.000) as well as lower levels of adiponectin (OR = 0.359, p value =0.000) and higher levels of leptin (OR = 1.469, p value =0.001)." (PMID 28878827, 2017). "Additionally, leptin is a key regulator of feeding behavior and has been tied to hypertension, abdominal obesity, dyslipidemia and other metabolic risk factors in certain populations." (PMID 29296187, 2017). "In the other hand, metabolic syndrome is found to be associated with higher levels of leptin." (PMID 28878827, 2017). "Other authors observed that in adults the wild-type variant of Q223R correlated not only with leptin concentrations but also with higher BMI and body fat, impaired glucose metabolism and dyslipidemia, as well as lower respiratory quotient during low-intensity exercise." (PMID 27240401, 2016). "Increased leptin levels were associated with elevated uric acid levels, and leptin might be a useful marker of the metabolic syndrome in adolescents." (PMID 28105014, 2016). "Therefore, in this study, we aimed to examine the effects of intravenous (i.v.)BCG administration on the development of metabolic syndrome in leptin-deficient ob/ob mice." (PMID 26039731, 2015). "Leptin-deficient mice are a well characterized model for analysing the metabolic syndrome." (PMID 25144618, 2014). "In addition to leptin abnormalities, metabolic syndrome is associated with depressed plasma adiponectin levels and dyslipidemia." (PMID 25168868, 2014). "Obese patients with three risk factors for metabolic syndrome have lower leptin levels." (PMID 24795698, 2014). "We have previously shown that exposure to a high-fat diet (HFD) in utero may cause a metabolic syndrome-like phenomenon through epigenetic modifications of adipocytokine, adiponectin and leptin gene expressions." (PMID 24664181, 2014). "In this study, we could show that FTO is a factor which contributes substantially to the development of the obese phenotype in leptin-deficient mice and thus to the metabolic syndrome as exemplified by hyperglycaemia and increased lipid content in liver." (PMID 25144618, 2014). "LEPR Gln223Arg polymorphism impacted leptin concentrations, and this gene polymorphism may influence susceptibility to metabolic syndrome among Thais." (PMID 24444121, 2014). "It is important to determine the hepatic transcriptional changes associated with the leptin rescue, since these may be useful biomarkers for metabolic syndrome and/or for the predisposed state seen in UN/Sal/Chow." (PMID 24447410, 2014). "Finally, we did not measure hormones, which are involved in the association between sleep quality and metabolic syndrome, such as insulin resistance, sympathoadrenal activity, ghrelin and leptin." (PMID 23342127, 2013). "However, previous studies have shown that high plasma leptin level is associated with the development of essential hypertension, hyperinsulinemia and dyslipidemia." (PMID 23514611, 2013). "The independent association between serum leptin and metabolic syndrome among older women also suggests that the etiology of metabolic syndrome among men and women may be somewhat different and require separate approaches for its prevention." (PMID 24455217, 2013). "In women, log leptin remained significantly associated with the risk of metabolic syndrome at year 6 after adjustment for potential confounders and adiposity measures (BMI, abdominal visceral fat, and total percent fat) at year 6 (OR 1.75; CI 1.004 to 3.032; P = 0.04)." (PMID 24455217, 2013). "Availability of detailed information on anthropometry including total body fat as measured by DEXA and abdominal visceral and abdominal subcutaneous fat as measured by CT scan allowed us to study the association of leptin with metabolic syndrome after controlling for body fat distribution." (PMID 24455217, 2013).
metabolic syndrome (continued). "Additionally, the positive association of leptin and metabolic syndrome among older women with normal BMI, in our study, suggests that older women with elevated serum leptin levels are at increased risk of metabolic syndrome even at normal weight." (PMID 24455217, 2013). "Additionally, serum leptin levels have been linked to individual components of the metabolic syndrome in cross-sectional studies." (PMID 24455217, 2013). "The association between leptin and metabolic syndrome is not fully understood." (PMID 22533665, 2012). "Interestingly, a locus on murine chromosome 4 has been associated with markers of the Metabolic Syndrome, including body weight, insulin, leptin and triglyceride." (PMID 22078008, 2011). "Furthermore, in the Framingham Third Generation Cohort, leptin concentrations were associated with increased odds of metabolic syndrome." (PMID 21526991, 2011). "After adjusting for age, an association between leptin levels and metabolic syndrome was observed." (PMID 21526991, 2011). "Dyslipidemia, IR and high levels of leptin were also associated with MS in this young group." (PMID 20537155, 2010). "Ameliorating “renal leptin resistance” or reducing leptin level and/or leptin signaling in states of chronic hyperleptinemia may be a novel strategy for the treatment of arterial hypertension associated with the metabolic syndrome." (PMID 21286276, 2010). "Similarly, PROSPER findings on other risk factors (e.g., leptin) or risk criteria (e.g., metabolic syndrome) are also in line with observational studies conducted in younger populations." (PMID 19554082, 2009). "In conclusion, treatment of a leptin-deficient child with r-metHuLeptin was beneficial, leading to improvements in neurocognition, substantial weight loss, decrease in caloric intake and normalization of the parameters of metabolic syndrome." (PMID 18769731, 2008). "These support the notion that insufficient leptin action may be a cause of metabolic syndrome, and that adequate leptin derived from SCAT is protective." (PMID 15530168, 2004). "A single central administration of a recombinant adeno-associated virus vector encoding the leptin gene significantly reduced adiposity and improved metabolic syndrome (MetS) symptoms in various models over an extended period." (PMID 39897330, 2025). "Hence, these circulating adipokines were analyzed in the serum of breast cancer survivors to determine their potential as a biomarker for lymphedema; additionally, the adiponectin/leptin ratio was calculated to evaluate the degree of association of metabolic syndrome with BCRL." (PMID 36232660, 2022). "After determining the reference interval of leptin levels, our further analysis showed that, in the normal BMI participants, individuals with leptin levels higher than the 97.5th percentile may have a higher risk of prevalent metabolic syndrome and abdominal obesity." (PMID 35941672, 2022). "However, increased circulating leptin is positively linked to metabolic syndrome in women." (PMID 34436440, 2021). "To determine whether dyslipidemia could contribute to preventing leptin for glucose-lowering effects in insulin-deficient RIP-CreΔLEPR mice, we first measured circulating FFAs, ketone bodies, glycerol, and TG in RIP-CreΔLEPR-LEP at 10 days after the beginning of leptin administration." (PMID 33071988, 2020). "Thus, galectin-12, resistin, leptin, and other adipokines/cytokines regulated by PPARγ may act synergistically to affect lipid metabolism in metabolic tissues, contributing to the dyslipidemia associated with APL." (PMID 32929351, 2020). "This ratio could be an atherosclerotic risk maker while the adiponectin/leptin ratio could be a valuable complementary element in prediction and prevention of cardiovascular diseases and metabolic syndrome, suggesting that our therapy was effective to improve these parameters." (PMID 31214594, 2019).
metabolic syndrome (continued). "Among them, leptin and adiponectin may be risk markers of fat-induced dyslipidemia and IR." (PMID 30305835, 2018). "Circadian disruption, which is typically induced by shift work, may negatively affect health due to impaired glucose and lipid homeostasis, reversed melatonin and cortisol rhythms, dysregulation of leptin and ghrelin, more severe metabolic syndrome, and clock gene rhythm loss." (PMID 25861266, 2015). "Exposure to a high fat diet in utero in mice induces the phenotype of type 2 diabetes and hypertension, which can be transmitted to the progeny and may cause a metabolic syndrome-like phenomenon through epigenetic modifications of adipocytokine, adiponectin and leptin gene expressions." (PMID 24664181, 2014). "The prevalence of metabolic syndrome increases with aging and since hyperleptinemia predicts body fat and is also linked to metabolic syndrome elevated serum leptin levels may become a useful biomarker for predicting the risk of metabolic syndrome at the population level among older women." (PMID 24455217, 2013). "The primary objective of this study is to examine the association between serum leptin and the development of metabolic syndrome over a 6-year follow-up in a cohort of older adults and to examine whether such an association is independent of markers of inflammation and body fat depots." (PMID 24455217, 2013). "Thus, the gender difference in the association of serum leptin with metabolic syndrome in our study may be explained by relatively greater leptin insensitivity in women." (PMID 24455217, 2013). "Multivariate regression analyses for the associations of circulating adiponectin, E2, leptin, 1,25(OH)2D3 levels and metabolic syndrome (MetS)." (PMID 23555948, 2013). "The elevated concentration of circulating leptin has been consistently associated with other cardiometabolic risk factors, such as hypertension, insulin resistance, and type 2 diabetes; however, few studies have analyzed its association with metabolic syndrome." (PMID 21526991, 2011). "Correlation heatmap and network analyses demonstrated interconnected clusters linking visceral adiposity, IR, dyslipidemia, adipokine imbalance, and neurotrophins, with the leptin/adiponectin ratio emerging as a central integrative marker." (PMID 41828655, 2026). "This is in line with the (non-significant) higher probability of pubertal children being in the “dyslipidemia & high leptin” status and lower probability of being in the “low leptin/IGF-1/HbA1c” status in our study." (PMID 39899498, 2025). "Leptin pathway is clarified as a crucial target for anthocyanins to protect against metabolic syndrome." (PMID 40478326, 2025). "Higher leptin with greater UPF intake was observed in older adults with metabolic syndrome in Spain (n = 92) and in a primary-care adult sample in Ireland (n = 1986)." (PMID 41010537, 2025). "Anthocyanins can also ameliorate the development of metabolic syndrome by improving the hypertrophy and inflammatory status of adipose tissue by regulating the leptin signaling pathway." (PMID 40626227, 2025). "The mean BMI z-score of the child, but also maternal BMI were highest in children in the “dyslipidemia/high leptin” status while being lowest in the “low leptin/IGF-1/HbA1c” status." (PMID 39899498, 2025). "Children of parents with a low/medium ISCED level showed an increased risk of being in the “inflammation” (1.55 [1.09;2.19]; OR and CI) or “dyslipidemia/high leptin” status (1.49 [1.01;2.21]) at age 8 with the effect increasing with age." (PMID 39899498, 2025). "In our study, we identified four distinct biomarker statuses based on comprehensive data and repeatedly collected blood samples of a large European children cohort including: “normal”, “low leptin/IGF-1/HbA1c”, “inflammation” and “dyslipidemia/high leptin”." (PMID 39899498, 2025).
metabolic syndrome (continued). "For instance, in metabolic syndrome (MetS) and type 2 diabetes (T2D), increased BChE levels correlate with markers such as leptin, glucose, cholesterol, inflammatory mediators like interleukin-6 (IL-6), and oxidative stress indicators such as superoxide anion." (PMID 40612057, 2025). "Additional significant biomarkers related to metabolic syndrome include adipokines like adiponectin and leptin." (PMID 41561332, 2025). "Children in the “inflammation” and “dyslipidemia/high leptin” status were particularly characterized by higher BMI, higher number of medias in the bedroom, lower parental education and not being a sports club member in our study." (PMID 39899498, 2025). "In line with previous studies we found that the mean BMI z-scores were highest in children in the “dyslipidemia/ high leptin” group." (PMID 39899498, 2025). "Leptin resistance at the hypothalamic level, which is often present in individuals with metabolic syndrome, can exacerbate neuroinflammation by disrupting the normal regulation of energy balance and immune responses." (PMID 40095902, 2025). "Notably, telmisartan treatment decreased leptin release from adipose tissue, thereby supporting our model and implicating a hitherto unknown mechanism that contributes to leptin-associated nephropathy in metabolic syndrome." (PMID 41474553, 2025). "Blood sugar levels, thyroid profiles, lipid profiles and serum leptin levels were measured andcompared between the metabolic syndrome and control groups." (PMID 40255297, 2025). "Longer total breast-feeding duration increased the likelihood for being in the “inflammation”, “dyslipidemia & high leptin” and “low leptin/IGF-1/HbA1c” status compared to the “normal” status in our study." (PMID 39899498, 2025). "The “inflammation” group in our study was characterized by slightly higher BMI than the “normal” and “low leptin/IGF-1/HbA1c” group but lower BMI as compared to the “dyslipidemia/high leptin” group." (PMID 39899498, 2025). "We specifically examined how the DLQI index related to metabolic syndrome indicators, triglyceride levels and leptin concentrations." (PMID 40003621, 2025). "The observed decrease in serum leptin levels, coupled with an increase in adiponectin, highlights the herb’s role in restoring adipokine balance in the context of metabolic syndrome." (PMID 41347218, 2025). "The biomarker status “dyslipidemia/high leptin” was characterized by higher triglycerides, leptin, IGF-1 and lower HDL-cholesterol concentrations as compared to the “normal” status." (PMID 39899498, 2025). "Based on the present study, olanzapine administration resulted in weight gain, dyslipidemia, hypertension, increased leptin levels, high blood sugar, and motor impairment." (PMID 40969408, 2025). "Subsequent studies confirmed that the leptin-adiponectin axis plays a pathophysiological role in increased systemic inflammation and oxidative stress observed in patients with metabolic syndrome." (PMID 40724644, 2025). "The imbalance between elevated leptin levels and reduced adiponectin levels, known as ‘leptin-adiponectin axis dysregulation,’ creates a synergistic effect in metabolic syndrome patients, accelerating CRLM." (PMID 41164182, 2025). "The dependent variables included metabolic syndrome (MS), triglycerides (TG) and leptin (LEPTIN) values measured after one year." (PMID 40003621, 2025). "Apart from staying in the same status, children in the “normal” status at T0 had a high probability (14%) of moving to the “dyslipidemia/high leptin” status at FU." (PMID 39899498, 2025). "Studies have revealed that visceral adipose tissue can accelerate the development of metabolic syndrome by releasing various bioactive compounds and hormones, such as lipocalin, leptin and interleukin." (PMID 38826810, 2024). "Associations were observed among leptin, adiponectin, and GGT, highlighting their combined role as potential markers for metabolic syndrome in children." (PMID 39771030, 2024).